RNU6-165P (RNA, U6 small nuclear 165, pseudogene)
Gene: Small nuclear RNA gene on chromosome 19 (53,766,534 to 53,766,632, reverse strand). Ensembl gene ENSG00000252979.
Homologues: Orthologues: chimpanzee U6 (99% identical), guinea pig U6 (75% identical). Paralogues in human: RNU6-1041P (80% identical), RNU6-1316P (80% identical), RNU6-726P (80% identical), RNU6-751P (80% identical), RNU6-982P (80% identical), RNU6-1175P (79% identical), RNU6-11P (79% identical), RNU6-28P (79% identical), RNU6-37P (79% identical), RNU6-86P (79% identical), RNU6-1022P (78% identical), RNU6-1067P (78% identical), and 1285 more.